DNMT1 (DNA methyltransferase 1)
Diseases named in the same sentence as DNMT1 in open-access papers (continued):
Sharing a sentence is not in itself a finding about the gene and the disease.
leukemia (80 papers, 2006 to 2025). A malignant (clonal) hematologic disorder, involving hematopoietic stem cells and characterized by the presence of primitive or atypical myeloid or lymphoid cells in the bone marrow and the blood. "Previous mechanistic studies of AZA resistance in human leukemia cell lines found that the mRNA levels of the genes encoding DNMT1, DNMT3a, and DNMT3b were increased in HMA-resistant cells." (PMID 38731939, 2024). "Because our previous studies suggested that DNMT1 upregulation and DNA hypermethylation are significantly and positively associated with more aggressive leukemia growth and worse prognosis, we examined the growth status of TQ-treated cells." (PMID 28415607, 2017). "The frequent occurrence of TET and DNMT1 mutations in leukemia suggests that genetic instability caused by R-loops could contribute to leukemia development, including through alterations in DNA methylation pathways." (PMID 36983041, 2023). "Upregulated DNMT1 could induce abnormal regional hypermethylation, and cause the pathogenesis of leukemia." (PMID 36797244, 2023). "Importantly, Dnmt1 knock-out or loss of function delays leukemia onset, indicating that functional DNMT1 is required for the self-renewal of both healthy and leukemic stem cells and, therefore, is also implicated in leukemic progression." (PMID 36497471, 2022). "Although DNMT1 inhibitor, Decitabine, has received FDA approval for the treatment of leukemia, discovering more DNMT1 inhibitors for cancer therapy is needed." (PMID 40050970, 2025). "This evidence prompted us to investigate the induction of apoptosis via DNMT1 inhibition in CCRF-CEM leukemia cells." (PMID 39595939, 2024). "KG-1 CMV-luc leukemia cells were treated with compound 4 to study its ability to demethylate CMV promoter via the inhibition of DNMT1 and reactivate the luciferase reporter gene." (PMID 39595939, 2024). "Extracts from K562 leukaemia cell model, showing high levels of DNMT1, were incubated with biotin-tagged DNMT1 bait, Ce-49 sh or Ce-10-2 sh and the complexes were purified on streptavidin-coated beads, followed by immunoblotting with anti-DNMT1 antibody." (PMID 36609400, 2023). "Trichostatin A (TSA) inhibited the expression of DNMT1 (DNA methyltransferase 1) via reduction of DNMT1 mRNA stability in Jurkat T leukemia cells." (PMID 36969235, 2023). "To dissect the binding preference of DNMT1 to various RNAs, we performed DNMT1 fRIP-seq in two different human cell lines, the leukemia cell line K562 and induced pluripotent stem cells (iPSCs)." (PMID 36574982, 2023). "To assess the role of these enzymes in the methylation of CAT promoter in leukemia cells, first we characterized DNMT1, DNMT3A, TET1-3 mRNA expression levels in CLL and HD B cells." (PMID 36112236, 2022). "MLL-AF9-induced AML depends on DNMT1 in transformation giving rise to leukaemia, maintenance of established leukaemia, and re-establishment of leukaemia by transplanting L-GMPs." (PMID 35838271, 2022). "Accumulating evidence indicates that the expression of DNMT1 is critical to leukaemia progression, but few agents target the key regulators or axis related to the DNMT1 gene." (PMID 35838271, 2022). "Not only does the overexpression of DNMT1 exist in solid tumours and promote the occurrence of adverse events, but a similar phenomenon has also been observed in leukaemia." (PMID 35838271, 2022). "This connection between CCDC26 and DNMT1 can provide the missing link between frequent mutations in CCDC26 locus and leukemia." (PMID 33851096, 2021). "HDAC inhibitors decrease the expression of EZH2 and DNMT1 and increase hypomethylating agent-mediated apoptosis in human leukemia cells." (PMID 33743723, 2021). "A recent study has shown that TQ exerts in vitro cytotoxicity effects against leukemia by inhibiting the activity of DNMT1 and inducing global DNA hypomethylation." (PMID 33922029, 2021).
leukemia (continued). "By contrast, bone marrow AML cells harvested at the time of progressive leukemia on these therapies demonstrated failure to deplete DNMT1 as measured by flow-cytometry." (PMID 32770088, 2021). "Curcumin was reported to induce global hypomethylation in MV4-11 leukemia cell line through molecular docking with DNMT1, suggesting that this compound covalently blocks the catalytic thiolate of DNMT1, inhibiting DNA methylation." (PMID 29706891, 2018). "Further, exposure of leukemia cell lines and patient primary cells to TQ resulted in DNMT1 downregulation, mechanistically, through dissociation of Sp1/NFkB complex from DNMT1 promoter." (PMID 28415607, 2017). "Our study for the first time demonstrates that DNMT1-dependent DNA methylation mediates the anticancer actions of TQ, opening a window to develop TQ as a novel DNA hypomethylating agent for leukemia therapy." (PMID 28415607, 2017). "Haploinsufficiency of DNMT1 also delays leukemia progression and inhibits self-renewal of leukemia stem cells." (PMID 27259275, 2016). "Emerging data indicate that the DNMTs, including DNMT1, DNMT3a, and DNMT3b, which catalyze promoter methylation, are upregulated in leukemia." (PMID 26673819, 2016). "Inactivation or silencing of NF-kB diminished, whereas exogenous expressed NF-kB increased promoter activity and gene expression of DNMT1 in human leukemia cells demonstrating nucleolin-NF-kB-DNMT1 axis as a new molecular pathway implicated in leukemogenesis." (PMID 27421653, 2016). "The inhibition of HDAC is associated with decrease of nuclear DNMT1 protein level due to downregulation of DNMT1 expression which has been observed in Jurkat leukemia T cells." (PMID 26703571, 2015). "The change of NFκB positively matches the alterations of DNMT1 promoter activity and endogenous DNMT1 expression in leukemia cells." (PMID 25015109, 2014). "Together, these findings indicate that DNMT1 expression in leukemia cells is controlled, at least partially, by a NCL-NFκB axis." (PMID 25015109, 2014). "For example, cKO of Dnmt1 in mice with leukemia blocks further development of pre-existing leukemia." (PMID 24172544, 2013). "Overexpression of DNMT1 and DNMT3a, coupled with suppression of MS and TET1, may drive the aberrant epigenetic modifications associated with leukemia development." (PMID 41254398, 2025). "Furthermore, haploinsufficiency of DNA methyltransferase 1 (Dnmt1) has been shown to effectively impair the self-renewal capabilities of leukemia stem cells while largely leaving normal hematopoiesis unaffected." (PMID 40099195, 2025). "CLSPN interact with DNMT1 to mediate decitabine response in leukemia." (PMID 41424711, 2025). "A previous in vivo study has shown that DNMT1 has a crucial role in MLL-AF9 leukemia development." (PMID 37573395, 2023). "The phenomena of DNMT1 alteration have been frequently observed in leukemia and lymphoma." (PMID 36797244, 2023). "Moreover, TQ was shown to interact with the catalytic pocket of DNMT1 and to exert in vitro cytotoxicity effects against leukemia by inhibiting the activity of DNMT1, inducing global DNA hypomethylation." (PMID 35566130, 2022). "In addition, DNMT1 is considered to be involved in tumorigenesis of several types of cancer, leukemia/lymphoma, and multiple solid tumors, including TNBC." (PMID 35008411, 2022). "According to research findings, DNMT1 sustains a higher level of expression in leukaemic stem cells (LSCs) compared with chemo-sensitive leukaemia cells, which could maintain the self-renewal of LSCs and regulate the biological functions of LSCs." (PMID 35838271, 2022). "Interestingly, in blasts of leukemia patients, TQ decreased the expression of DNMT1 and DNMT3A at both the mRNA and protein levels and induced apoptosis." (PMID 33922029, 2021). "Indeed, deletion of Dnmt1 prevents the development of MLL-AF9 leukemia in vivo, suggesting that MLL fusion proteins require maintenance methylation, but not de novo methylation, for leukemia induction." (PMID 31527484, 2019).
leukemia (continued). "Recent studies indicate that DNMT1 is essential for maintenance of stem cells and CSCs, such as haematopoietic stem cells (HSCs)/progenitor cells, epidermal progenitor cells, mesenchymal stem cells and leukemia stem cells." (PMID 29721170, 2018). "We identified DNMT1-assoicated DNA methylation as a hitherto unknown molecular rule mediating the anti-leukemia actions of TQ." (PMID 28415607, 2017). "Overexpression of DNMT1 contributes to pathogenesis of leukemia." (PMID 26384351, 2015). "Furthermore, halving the level of Dnmt1 in wild-type mice leads to impaired leukemia stem cell self-renewal and survival, probably from hypomethylation and derepression of a number of tumor suppressor genes." (PMID 24172544, 2013). "That mutations in DNMT1 should cause adult-onset neurological defects without involvement of other tissues is unexpected; partial loss-of-function alleles of Dnmt1 in mice cause pervasive developmental delays and high rates of leukemia without obvious neurological abnormalities." (PMID 28503201, 2017). "Notably, the conditional knockout of DNMT1 hinders leukemia development." (PMID 27259275, 2016). "This study demonstrates a DNMT1 downregulation in CML cells; however, there have been instances in which DNMT1 is upregulated in leukemia." (PMID 40004944, 2025). "Some of these target genes include DNMT1 (DNA Methyltransferase 1), FLT3 (FMS-Like Tyrosine Kinase 3), and MLL (Mixed-Lineage Leukaemia)." (PMID 38902412, 2024). "In leukemia cells, FABP4 regulates DNMT1 expression through the IL-6/STAT3 axis and DNMT1 controls FABP4 through VEGF signaling, thereby forming a mutually reinforcing positive feedback regulation that ultimately promotes AML aggressiveness." (PMID 36106108, 2022). "To test this, we treated leukemia cells, including ML-1, Kasumi-1 and MV4-11, with indicated doses of TQ and initially employed Western blot to assess DNMT1 changes." (PMID 28415607, 2017). "Decitabine, a hypomethylating agent, inhibits DNA methyltransferase 1(DNMT1), reactivates of silenced genes, and induces differentiation of leukemia cells." (PMID 25749041, 2015). "Further evaluation revealed that these compounds were more potent against human DNMT3A than against human DNMT1 and induced the re-expression of a reporter gene, controlled by a methylated cytomegalovirus (CMV) promoter, in leukemia KG-1 cells." (PMID 24678024, 2014). "By analyzing the GEO datasets, we found that NCL levels are in parallel with the expression of DNMT1, DNMT3A and DNMT3B in leukemia patients." (PMID 25015109, 2014). "DNMT1, the most important DNMT for maintaining the aberrant methylation, had been found to be aberrantly elevated not only in leukemia but also in many types of cancer cells." (PMID 19897545, 2011). "Besides, PTL has other biological abilities, such as inducing global DNA hypomethylation via specifically suppressing DNA methyltransferase 1 (DNMT1) activity in vitro and in vivo and showing high potency against leukemia." (PMID 35514960, 2022). "The consistency of the acute metabolic responses enabled exploitation: simple treatment modifications in xenotransplant models of chemorefractory leukemia extended noncytotoxic DNMT1-depletion and leukemia control by several months." (PMID 32770088, 2021). "Conditional knockout of Dnmt1 blocks development of leukemia, and haploinsufficiency of Dnmt1 is sufficient to delay progression of leukemogenesis and impair leukemia stem cell (LSC) self-renewal without altering normal hematopoiesis." (PMID 25886310, 2015). "In all, our results demonstrated that NCL overexpression enhances NFκB activity and subsequently promotes DNMT1 expression, which is followed by global DNA hypermethylation and epigenetic silencing of TSG transcription, thus, conferring a survival advantage to leukemia cells." (PMID 25015109, 2014).
leukemia (continued). "This work strongly suggests that a direct pharmacological inhibition of DNMT1, unlike the use of 5-aza-2′-deoxycytidine, should lead to tumor suppressor gene hypomethylation and re-expression without inducing major DNA damage in leukemia." (PMID 25948775, 2015). "Aside from cytotoxic effects, azacytidine also induces DNA demethylation by inhibiting DNA Methyltransferase 1 (DNMT1) after being incorporated into the DNA and nanomolar doses can reduce self-renewing and leukemia-initiating capacities without leading to direct cytotoxic effects." (PMID 34857808, 2021).
melanoma (63 papers, 2010 to 2026). A malignant, usually aggressive tumor composed of atypical, neoplastic melanocytes. "Our results indicated that low ac-DNMT1 protein levels are significantly associated with a poor MSS in patients with stage IV melanoma." (PMID 34572918, 2021). "Recently, two variants in the RORA locus were found to be associated with melanoma prognosis, rs782917 and rs17204952 as well as rs7253062 in DNMT1, a steroid hormone receptor as well." (PMID 33549124, 2021). "By analyzing gene expression microarray data generated from a series of melanoma cell lines, we found that CG gene activation is correlated with the presence of a gene expression signature that has been previously associated with DNMT1 depletion." (PMID 26504497, 2015). "A first line of evidence was provided by our observation that activation of CG genes in melanoma cells correlates with the presence of a gene expression signature that has been previously associated with DNMT1 depletion." (PMID 26504497, 2015). "Together, our observations point towards transient DNMT1 depletion as a causal factor of CG gene activation in vivo in melanoma." (PMID 26504497, 2015). "Together our results indicate that CG gene activation in melanoma tissues is associated with reduced expression of DNMT1." (PMID 26504497, 2015). "A second line of evidence implicating transient DNMT1 depletion as a causal factor of CG gene activation in melanoma was provided by careful examination of expression data deriving from a large set of melanoma tissues." (PMID 26504497, 2015). "Importantly, we now provide evidence that a process of DNMT1 depletion actually occurs in vivo in melanoma and is linked with CG gene activation." (PMID 26504497, 2015). "Additionally, decreased ac-DNMT1 protein levels were associated with melanoma progression." (PMID 34572918, 2021). "Additionally, reduced ac-DNMT1 protein levels were associated with melanoma progression." (PMID 34572918, 2021). "Hou and colleagues could demonstrate that oncogenic BRAF V6000E in melanoma causes a large number of epigenetic alterations, including decreased expression levels of DNA-methyltransferase 1 (DNMT1) and histone methyltransferase EZH2 affecting CpG island methylation and the epigenetic landscape." (PMID 32046099, 2020). "BRAF-mutant melanoma with acquired resistance to vemurafenib showed increased levels of DNMT1, which is an eminent epigenetic factor in melanoma progression." (PMID 39935431, 2025). "DNMT1 degradation by vorinostat treatment reduced cell viability both in sensitive and vemurafenib-resistant melanoma cells." (PMID 39935431, 2025). "For example, the depletion of DNMT1 in human melanoma cells led to hypomethylation and re-expression of the germ line-specific MAGE-A1 transgene, commonly suppressed in melanoma." (PMID 40136320, 2025). "They initially validated the expression of miR‐211 in melanoma cell lines and noted a positive correlation between its reduction and enhanced DNMT1 expression." (PMID 40387409, 2025). "Genetic ablation of Mll4 in murine melanoma cells leads to reduced expression of Dnm3a and Dnmt1 via attenuating their enhancer activities." (PMID 36323669, 2022). "This corroborates recent findings that correlated G9a- and DNMT1-activity to melanoma cell proliferation." (PMID 35634329, 2022). "DNMT1 mRNA levels were significantly increased in primary melanoma tumors compared to nevus (p < 0.0001) or normal skin tissues (p = 0.003)." (PMID 34572918, 2021). "The acetylated DNMT1 (ac-DNMT1) protein level was assessed using an anti-acetylated lysine antibody in a clinically annotated melanoma patient tumor specimen cohort." (PMID 34572918, 2021). "After panobinostat treatment, we observed an accumulation of ac-DNMT1 and reduced DNMT1 protein expression in melanoma cell lines." (PMID 34572918, 2021). "Metastatic melanoma showed an increase in DNMT1 mRNA expression compared to primary melanoma (p < 0.0001)." (PMID 34572918, 2021).